IGF1 (insulin like growth factor 1)
Diseases named in the same sentence as IGF1 in open-access papers (continued):
Sharing a sentence is not in itself a finding about the gene and the disease.
Ewing sarcoma (continued). "In the case of Ewing's sarcoma, IGF-1R is ubiquitously expressed and its activation is sustained by the autocrine production of IGF1 by tumour cells." (PMID 21647361, 2011). "The amount of IGF-1 and IGF-BP3 secreted into the culture media by Ewing's sarcoma cell lines was measured by ELISA." (PMID 22022506, 2011). "This promoter region has been shown to be functional or to at least contain functional portions of the promoter in different IGF1 expressing cells, including macrophages and the EWS-FLI-1 expressing Ewing's sarcoma cell line SK-N MC." (PMID 18648544, 2008). "IGF1R was early identified as a target in Ewing sarcoma, as the IGF1R was highly expressed in Ewing sarcoma cell lines in addition to the expression of IGF1, which may thus signal in an autocrine loop." (PMID 33260481, 2020). "IGF-1 and IGF-1R expression are elevated in Ewing sarcoma cell lines and tumors." (PMID 29321818, 2017). "Additionally, IGF1 is among a small subset of genes commonly activated by EWS-FLI1 and other Ewing sarcoma fusion proteins, such as EWS-ERG, underscoring its significance in this disease." (PMID 27259270, 2016). "Moreover, when Ewing sarcoma cells were exposed to exogenous IGF1 and/or insulin, metformin prevented IGF-1 and Insulin-induced proliferation and maintained its anti-proliferative effects." (PMID 24391834, 2013). "The EWSR1-FLI1 fusion gene is thought to function as a regulator of the expression of insulin-like growth factor 1 (IGF1), and overexpression of IGF1 receptor (IGF1R) is observed in Ewing sarcoma cells; the IGF1R pathway could thus be a target in Ewing sarcoma cases." (PMID 35408900, 2022). "However, gene signatures associated with response to robatumumab in tissues from Ewing sarcoma patient responders, non-responders and controls, identified genes were associated with mTOR and Akt action but not the IGF1R and IGF1." (PMID 34440844, 2021). "We also noticed that Ewing sarcoma cell lines expressing low levels of IGF1R, such as A673, were less sensitive to JQ1 in comparison to IGF1R-overexpressing lines, underscoring the significance of the IGF1 autocrine mechanism as a key target of BET inhibitors in Ewing sarcoma." (PMID 27259270, 2016). "Also, the link between IGF1 expression and BET proteins appears to be unique to Ewing sarcoma (unpublished results), which is consistent with the unique ability of EWS-FLI1 to stimulate IGF1 expression in Ewing sarcoma." (PMID 27259270, 2016). "For this, human rhabdomyosarcoma (Rh30) and Ewing sarcoma (Rh1) cells were primarily chosen as models, because these cells, under autocrine conditions, are able to produce large quantity of IGF-II, which has approximately equal affinity to IGF-1 receptor as IGF-1." (PMID 25762619, 2015). "However, IGF1 at 0.2–20 ng ml−1 neither increased the colony-forming ability and proliferative activity of Ewing tumour cells under serum-free conditions, nor was IGF1 sufficient to protect TC-71 cells from FGF2-induced apoptosis (data not shown)." (PMID 15685229, 2005). "The serum effect could not be attributed to IGF1, a growth factor thought to be one of the key mitogenic and survival factors in Ewing tumours." (PMID 15685229, 2005). "Mimicking Ewing sarcoma in mice has been challenging, however, a recent mouse model showed that while EWSR1::FLI1 may be sufficient for tumorigenesis, subsequent YAP1 activation induced by IGF1 signalling may be required for the activation of TEAD driven transcription and metastatic progression." (PMID 40442778, 2025). "The difference of IGF-1 level between high-grade (497.7 ± 21.73) vs low-grade (406.7 ± 28.47) (P=0.003), metastatic (542.6 ± 34.86) vs non-metastatic (435.1 ± 85.83) (P=0.004) and recurrent (565.9 ± 40.89) vs non-recurrent (437.4 ± 17.14) (P=0.004) Ewing sarcoma tumors was statistically significant." (PMID 36713521, 2022).
Ewing sarcoma (continued). "Additionally, in Ewing sarcoma, patients with metastatic disease exhibited lower IGF1 levels when compared to the localized disease, suggesting that further progression of the disease negatively modulates IGF1 levels, which would explain the higher EFS in patients with higher IGF1 levels." (PMID 33260481, 2020).
Infertility (43 papers, 2006 to 2025). "Insulin-like growth factor 1 (IGF1) is also associated with endometrial morphogenesis and Igf1 null mutant female mice show a hypoplastic uterus and fail to ovulate, resulting in infertility." (PMID 35887546, 2022). "It has been shown that IGF1 deficiency causes infertility and hypoplasia of uterus in female mice, and it was suggested that IGF1 has main role in uterine growth and function." (PMID 35459174, 2022). "IGF1 knockout mice have severe growth retardation, deficiencies in bone and muscle development, infertility, and lethal respiratory failure due to lung hypoplasia, highlighting the importance of GH/IGF1 axis in different tissues development." (PMID 34943879, 2021). "In the mouse, targeted null mutation of the Igf1 gene encoding IGF-I results in infertility secondary to failure to ovulate even after administration of gonadotropins." (PMID 35118400, 2021). "The serum level of estrogen in IGF-1-deficient female mice appears significantly reduced, whereas in ERα-deficient mice, which are also infertile, there is a threefold increase." (PMID 17201918, 2007). "As a result, the downregulation of IGF-1 could be linked to the poor endometrial quality and infertility seen in women with CE, and may explain the histological changes frequently present in these women, such as the presence of polyps." (PMID 39941505, 2025). "Consumption of low-fat and skimmed milk can be associated with higher levels of insulin and insulin-like growth factor-1 and thus spermatogenesis, while the reason for the adverse effect of high-fat dairy on infertility can be ascribed to the high content of SFA." (PMID 35911859, 2022). "Furthermore, lower levels of NGF or IGF-1 in seminal plasma are associated with infertility." (PMID 38792459, 2024). "Furthermore, defects in insulin/IGF1 signaling can cause infertility." (PMID 36506051, 2022). "The search was conducted using combinations of keywords related to “NGF”, “EPO”, “IGF-1”, “male reproductive system”, “sperm, “sperm motility”, “sperm vitality”, “infertility”, and “ART”." (PMID 38792459, 2024). "The available data indicate that NGF, EPO, and IGF-1 positively influence sperm motility, and lower levels of NGF or IGF-1 in seminal plasma are associated with infertility." (PMID 38792459, 2024). "The levels of IGF-1 in the seminal plasma varies, being lower in infertile men or in smokers with OAT." (PMID 38792459, 2024). "In males, IGF-1 is necessary for the development of germ cells and normal morphology, while male mice with an IGF-1 null mutation are infertile." (PMID 38792459, 2024). "Colombo and Naz 1999 detected IGF-1 protein in seminal plasma of both fertile and infertile subjects." (PMID 38792459, 2024). "It has been reported recently that IGF-1 supplementation increased the sperm concentration, sperm volume, and sperm progressive motility of an infertile man." (PMID 37064267, 2023). "Though thus a good number of studies have investigated GH-supplementation in conjunction with IVF, peripheral IGF-1 values in infertile women have been only minimally explored and, indeed, with contradictory findings by the same institution.." (PMID 35066698, 2022). "Noteworthy, peripheral IGF1 concentrations in sub- or infertile women have been investigated only in few reports." (PMID 35626647, 2022). "IGF1 signaling in the ovary was initially thought to be mediated by insulin receptor substrate 2 (IRS2), as the deletion of the Irs2 gene caused infertility." (PMID 33808081, 2021). "This axis provided a new idea to elucidate the unexplained infertility due to an aberrant IGF-1 axis." (PMID 28706275, 2017). "The homeostasis of IGF-1 and IGFBP-1 clearly affects fertility, as shown by the infertility phenotype in both IGF-1-deficient mice and IGFBP-1 transgenic mice." (PMID 17201918, 2007). "Mice deficient in IGF-1 were infertile, show delayed bone development, weigh only about 30% of normal adult body weight, and have a high mortality rate." (PMID 40598150, 2025).
Infertility (continued). "It is likely that smoking effects on sperm parameters could be mediated by a reduction in seminal IGF-1, and this reduction is correlated with infertility." (PMID 38792459, 2024). "Interestingly, female IGF1-KO mice exhibit a hypoplastic uterus and an inability to ovulate, leading to infertility, which highlights the vital role of IGF-1 in uterine function and fertility." (PMID 39120268, 2024). "From this study, it was thought that, because of the low GH secretion levels in obese infertile patients, exogenous GH administration could increase the levels of GH and IGF-1, thereby promoting lipolysis and affecting fat volume and distribution." (PMID 36769605, 2023). "So far there is limited data available about the peripheral IGF1 concentrations in infertile women." (PMID 35626647, 2022). "Since cycle cancellation rates in this study clearly inversely correlated with IGF-1 levels, this study for the first time offers a potential selection tool for women in infertility treatments who may benefit from GH supplementation in association with IVF." (PMID 35066698, 2022). "Moreover, knockout of the IGF-1 gene in the mouse does results in infertility (and dwarfism), a phenotype that cannot be rescued with gonadotropin stimulation and on histology demonstrates a complete arrest in the development of the growing follicle pool." (PMID 35066698, 2022). "Different fasting regimens can reduce IGF-1, IGFBP1, glucose, and insulin levels and consequently have beneficial effects on ovarian function, androgen excess, and infertility in women with PCOS." (PMID 31603907, 2019). "In infertile smokers, significantly lower IGF-1 levels were observed, followed by infertile nonsmokers." (PMID 38792459, 2024). "For infertile PCOS patients with POR to exogenous gonadotropins, GH therapy may enhance their gonadal activity by increasing the activity of IGF-1." (PMID 37064267, 2023). "Female mice lacking IGF1 are infertile, and follicular development is arrested at the small antral stage." (PMID 36359088, 2022). "Female mice lacking IGF1 are infertile, with follicular development being arrested at the small antral stage." (PMID 33808081, 2021). "In IGF1-null mice, there are no mature large antral follicles produced and eventually resulting in infertile." (PMID 31480138, 2020). "Studies on Igf1 null mice reveal the development of immature ovaries concomitant with infertility and non-responsiveness towards exogenous gonadotropins, while in vitro administration of IGF1 promotes oocyte maturation, fertilization, and embryo development in bovine, canine and mice oocytes." (PMID 37457295, 2023).
acute kidney injury (41 papers, 2009 to 2024). Sudden and sustained deterioration of the kidney function characterized by decreased glomerular filtration rate, increased serum creatinine or oliguria. "In patients with CKD, age-related muscle loss is deepened by metabolic disorders associated with renal failure such as inadequate nutrient intake, loss of nutrients, catabolic illnesses, acidemia, inflammation, low levels of or resistance to anabolic hormones like insulin, growth hormone, and IGF-1." (PMID 29620449, 2018). "Another study showed that EA can reduce the levels of iNOS and HO-1/2 and upregulate IGF-1 levels, thus reducing glomerulosclerosis and renal interstitial fibrosis as well as blood pressure in rats with renal failure." (PMID 37675019, 2022). "Of note, above-average serum IGF-1 concentrations are encountered during normal pregnancy, puberty and the post-pubertal period, whereas below average IGF1 levels are seen in uncontrolled diabetes or renal failure." (PMID 34557164, 2021). "Preconditioning of mouse BMSCs with IGF-1 before infusion improved cell migration capacity and restored normal renal function after acute kidney injury." (PMID 31357692, 2019). "In a mouse acute kidney injury model, mouse BMSCs exert beneficial effects on tubular cell repair in acute kidney injury by producing the mitogenic and pro-survival factor IGF-1." (PMID 31357692, 2019). "In animal studies, IGF-1 overexpression has been shown to improve the therapeutic action of mesenchymal stem cells against acute kidney injury." (PMID 27138941, 2016). "Accelerated recovery from acute kidney injury using IGF-1 treatment was mediated by both increases in glomerular blood flow and tubular cell proliferation, and inhibition of apoptosis." (PMID 25811887, 2015). "IGF-1 may hold potential as a supportive therapy for preterm infants sensitive to acute kidney injury." (PMID 38762663, 2024). "A low IGF binding protein 3 (IGFBP3), such as in renal failure, may on the other hand cause a falsely normal or low IGF-2/IGF-1 ratio." (PMID 38432069, 2024). "IGF-1 rapidly normalized, but the patient presented with nausea, anorexia, and acute kidney injury." (PMID 38770226, 2024). "However, IGF1 sustains stem cell-mediated repair of tubular epithelial cells in acute kidney injury." (PMID 35385750, 2022). "This manuscript gives an overview of the physiological actions of GH and IGF-1 on the kidneys and summarizes the current knowledge of their impact on kidney health in subjects with normal and impaired kidney function, including acute kidney injury (AKI), CKD and nephrotic syndrome." (PMID 34143299, 2021). "Moreover, growth factors like HGF or IGF-1 showed therapeutic potential in animal models of acute kidney injury through multiple actions that may concur to create a pro-regenerative environment." (PMID 25811887, 2015). "In an acute kidney injury model, hAEC-ECV treatment resulted in significant upregulation of angiogenesis-related genes (Fgf, Hgf, Igf-1, Pdgf, and Vegf)." (PMID 35083233, 2021). "This study was undertaken to test two therapies for acute kidney injury (AKI) prevention, IGF-1, which is renal protective, and BTP-2, which is a calcium entry (SOCE) inhibitor." (PMID 32521790, 2020). "A low IGF binding protein 3 (IGFBP3), such as in renal failure, may also result in a falsely normal or low IGF-2/IGF-1 ratio." (PMID 38432069, 2024). "Further, when mice subjected to CSP-induced acute kidney injury were transplanted with IGF-1-depleted MSCs via tail vein, renal protection and tubular structure was found to be limited, suggesting that MSCs promote the repair of tubular cells via the secretion of IGF-1." (PMID 30294285, 2018).
asthma (41 papers, 2012 to 2025). "IGF1 is a known mitogen for airway SM cells, promoting proliferation and hypertrophy, being also implicated in airway remodeling in asthma." (PMID 41279414, 2025). "Together, these MR Results support the possibility of a causal relationship between elevated serum IGF-1 levels and asthma, and these conclusions are useful for clinical detection in patients with asthma." (PMID 36936149, 2023). "A study among British population cohort suggested that the level of serum IGF-1 was associated with a lower risk of asthma, which was in line with our study." (PMID 36936149, 2023). "Asthma patients treated with ICS have reduced IGF-1 levels, which is associated with reduced airway wall thickness and inflammation." (PMID 32509795, 2020). "IGF1 is produced by human bronchial epithelial cells in response to IL-17F, a cytokine implicated in asthma." (PMID 22235296, 2012). "However, a case-control study of 50 participants reported a positive association of serum IGF-1 with asthma." (PMID 36936149, 2023). "The present study demonstrated that circulating IGF-1 may be causally related to lower risk of asthma." (PMID 36936149, 2023). "Thus, observations from preclinical experimental studies implied that increased IGF-1 signaling may aggravate asthma risk, while findings from this study as well as other epidemiological studies indicated that IGF-1 may be associated with reduced asthma risk." (PMID 36936149, 2023). "The findings of this study demonstrated that IGF-1/AKT pathway was inhibited in SM in adolescent rats of asthma model, consistent with the retarded growth of SM mass." (PMID 39831118, 2024). "A Mendelian randomization analysis revealed that high levels of circulating insulin-like growth factor 1 (IGF-1) are associated with reduced risks of COPD and asthma." (PMID 38270119, 2023). "In the genetic correlation analysis, we found that adiponectin was only significantly associated with childhood-onset asthma, whereas CRP, IGF-1, leptin, and TNFR2 were only significantly associated with adult onset asthma." (PMID 36253437, 2022). "In asthma, IGF-1 modulates airway inflammation and hyper-responsiveness and airway smooth muscle hyperplasia, resulting in impaired lung mechanics." (PMID 36160852, 2022). "Accordingly, IGF1 was reported to be involved in airway inflammation and remodeling in asthma and increased in serum of asthmatic patients." (PMID 34440118, 2021). "IGF-1 mRNA level is significantly elevated in endobronchial biopsies from asthma patients and is correlated with subepithelial fibrosis, which is partly reversed by inhaled beclomethasone dipropionate." (PMID 30018981, 2018). "The production of granulocyte macrophage colony stimulating factor (GM-CSF), a recognized cytokine that maintains the inflammation and vascular leakage in asthma, is potentiated by IGF-1 in human ASM cells via p38 MAPK." (PMID 30018981, 2018). "Positive feedback between IGF-1 and Th2 cytokines has been documented in asthma, as IGF-1 is inducible by repetitive intranasal challenge with IL-25 or IL-33 in murine asthma models." (PMID 30018981, 2018). "Recombinant human IGF-1 directly stimulates proliferation of both human and mouse regulatory T cells (Treg) in vitro, which has been shown to regulate allergic responses in asthma." (PMID 30018981, 2018). "Although little is known about the role of IGFs in human asthma, IGF1 and IGFBP3 were suggested to be involved in allergic airway inflammation and remodeling." (PMID 29272313, 2017). "Airway inflammation and hyperresponsiveness are pathological features of asthma, and Klotho can inhibit the IGF-1 signaling pathway, which leads to reduced proliferation and contraction of airway smooth muscles, decreased airway hyperresponsiveness, and reduced airway resistance." (PMID 38287280, 2024).